ORAI1 (ORAI calcium release-activated calcium modulator 1)
Diseases named in the same sentence as ORAI1 in open-access papers (continued):
Sharing a sentence is not in itself a finding about the gene and the disease.
atherosclerosis (6 papers, 2017 to 2023). A disease characterized by the build-up of fatty material and calcium deposition in the arterial wall resulting in partial or complete occlusion of the arterial lumen. "The involvement of ORAI1 in lipid metabolism foreshadows its potential role in pathogenic mechanisms underlying atherosclerosis, including lipid deposition and formation of the fatty streak." (PMID 33937254, 2021). "A separate study has reported the significant role of Orai1 in atherosclerosis by its regulation of both vascular inflammation and foam cell formation." (PMID 37259313, 2023). "And in vivo studies revealed that inhibition of Orai1 SOCC attenuates the development of atherosclerosis." (PMID 37588590, 2023). "In conclusion, these studies propose that STIM1 and Orai1 are involved in atherosclerosis plaque development." (PMID 37259313, 2023). "This is further supported by the role of ORAI1 in immune cell function, inflammation, and lipid homeostasis, which are key components in the development of atherosclerosis and NIH." (PMID 33937254, 2021). "The rapidly increasing knowledge of the implications of ORAI1 signalling in vascular remodelling holds promise to generate novel therapeutic tools for atherosclerosis and to prevent NIH following endovascular intervention." (PMID 33937254, 2021). "Inhibition of Orai1 SOCC attenuates the development of atherosclerosis." (PMID 37588590, 2023). "STIM1 and Orai1 also play a role in atherosclerosis, with studies showing that an increased presence SOCE in VSMCs prior to development of atherosclerosis plaques." (PMID 37259313, 2023). "The involvement of ORAI1-mediated SOCE in normal platelet function implies the potential involvement of ORAI1 abnormalities in platelet activation and adhesion in atherosclerosis." (PMID 33937254, 2021). "Thus, the mechanisms by which chronic inflammation or hyperglycaemia lead to atherosclerosis involve an increase in endothelial permeability and proliferation that depend on STIM1 and Orai1." (PMID 36834672, 2023). "Selective expression of TRPC1-based SOCs and Orai1-based CRAC channels in distinct VSMC phenotypes may provide useful strategies for developing therapeutic strategies to treat distinct progression phases of cardiovascular diseases such as hypertension and atherosclerosis." (PMID 28301277, 2017).
Calcium nephrolithiasis (6 papers, 2012 to 2020). The presence of calcium-containing calculi (stones) in the kidneys. "In addition, the CC genotype of rs12313273 in ORAI1 was strongly associated with the risk and recurrence of calcium nephrolithiasis." (PMID 24745010, 2014). "Genetic polymorphisms of ORAI1, which codes for the main subunit of the store-operated calcium (SOC) channel, were reported to be associated with the risk and recurrence of calcium nephrolithiasis." (PMID 24800221, 2014). "Genetic polymorphisms of CLDN14, CASR, OPN, ORAI1, and VDR were reported to be involved in calcium nephrolithiasis in humans." (PMID 24800221, 2014). "Our previous study indicated that genetic polymorphisms of ORAI1, which codes for the main subunit of the store-operated calcium (SOC) channel, were associated with the risk and recurrence of calcium nephrolithiasis in a Taiwanese population." (PMID 24800221, 2014).
colitis (6 papers, 2017 to 2023). Inflammation of the colon. "E.g., the deletion of the plasma membrane proteins ORAI1 + 2 forming release-activated Ca2+ channels leads to the abolishment of store-operated Ca2+ entry and a decrease of intracellular Ca2+, and protects mice from allo-immunity in models of colitis and GVHD." (PMID 32849661, 2020). "Abolishing SOCE by combined deletion of Orai1 and Orai2 resulted in severe defects in T cell function in vitro and T cell-mediated immune responses in vivo including antibody production after viral infection, colitis and GvHD." (PMID 28294127, 2017). "Furthermore, Orai1/Orai2-deficient T cells did not cause immunopathology in adoptive transfer models of colitis and GvHD." (PMID 28294127, 2017). "Using a murine T cell transfer model of colitis, we show that deletion of the CRAC channel genes Stim1, Stim2, or Orai1 in T cells prevents IBD and that the severity of intestinal inflammation correlates with the level of SOCE." (PMID 35919953, 2022). "Nonfunctional Orai1 knock-in mice showed impaired Ca2+ influx in vitro and reduced delayed hypersensitivity and colitis in vivo." (PMID 35126366, 2021). "The histological analysis of intestinal inflammation showed severe colitis in host mice that had received wildtype or Stim2‐deficient CD4+ T cells, whereas inflammation was partially reduced or absent following transfer of Orai1‐deficient and Stim1‐deficient CD4+ T cells, respectively." (PMID 35919953, 2022).
COVID-19 (6 papers, 2021 to 2024). A disease caused by infection with severe acute respiratory syndrome coronavirus 2. "Further research is still needed to understand the role of ORAI1 in severe COVID-19 illness and to investigate the potential genetic association of ORAI1 variants and adverse COVID-19 outcome in different populations." (PMID 35113933, 2022). "The calcium ion channel ORAI1 has emerged as a promising therapeutic target for the Coronavirus Disease 19 (COVID-19)-associated pneumonia, and a pharmacological inhibitor of ORAI1 has now reached clinical trials for severe COVID-19 pneumonia." (PMID 35113933, 2022). "This important role in immune cell function and inflammation motivated us to examine the potential association between ORAI1 polymorphisms and the severity of COVID-19 illness." (PMID 35113933, 2022). "The genetic variants within the ORAI1 gene were examined for association with COVID-19 positivity." (PMID 35113933, 2022). "We then examined the association between ORAI1 variants and COVID-19 fatality." (PMID 35113933, 2022). "The well-established roles of ORAI1 in immune response and inflammation rendered it as a promising candidate gene that could be implicated in an altered susceptibility to COVID-19 positivity and disease severity." (PMID 35113933, 2022). "It is however still unknown if ORAI1 small nucleotide polymorphisms (SNPs) could be implicated in an increased risk of SARS-CoV-2 infection or COVID-19-associated fatality." (PMID 35113933, 2022). "Further studies are needed to investigate whether ORAI1 polymorphisms influence the susceptibility to COVID-19 positivity or fatality in different ethnic populations." (PMID 35113933, 2022). "ORAI1 is an interesting candidate gene in the context of COVID-19 as it is known to play a key role in the immune response, inflammation, platelet activation and thrombus formation." (PMID 35113933, 2022). "Our aim is to study the implications of host genetic polymorphisms within the ORAI1 gene in the genetic risk for SARS-CoV-2 infection and for the severity of COVID-19 symptoms." (PMID 35113933, 2022). "For example, the calcium ion channel gene ORAI1 is known for its role in immune response, inflammation, platelet activation and thrombus formation, and was therefore considered as a potential drug target for COVID-19." (PMID 38550926, 2023). "ORAI1 abundance was decreased in all of our COVID-19 patients compared to healthy controls." (PMID 37033961, 2023). "Therefore, this candidate gene association study investigates the potential associations of polymorphisms within the ORAI1 gene and the susceptibility to SARS-CoV-2 infection as well as COVID-19 fatality in UK Biobank dataset." (PMID 35113933, 2022). "The linkage between ORAI1, the immune, and inflammatory responses, as well as the fact that strong evidence implicates a hyper-inflammatory state in the adverse COVID-19 outcome, foreshadow a potential role of ORAI1 in the pro-inflammatory cytokine storm reported in severe COVID-19 illness." (PMID 35113933, 2022). "Here, we investigate the host genetic polymorphisms within the ORAI1 gene that could be implicated in the genetic risk for SARS-CoV-2 infection and for the severity of COVID-19 symptoms." (PMID 35113933, 2022). "Therefore, an impact of ORAI1 variants on COVID-19 fatality in different ethnic groups cannot be ruled out." (PMID 35113933, 2022). "We conducted in vitro experiments in healthy donor PBMCs to verify our findings on altered KCNA3, ORAI1, and STIM1 gene expression in dexamethasone-treated COVID-19 patients and confirmed that in vitro treatment with dexamethasone altered the abundance of these ion channel encoding genes." (PMID 37033961, 2023).
COVID-19 (continued). "In comparison to the COVID-19(-) PU controls, genes highly expressed in the TV group fell into categories that included neutrophil dysfunction (CD274, PADI2), inhibition of B and T cell responses (CD22, IRF4, ORAI1), and upregulation of pro-inflammatory response pathways (CARD8, MAPK7, IRF7, IFIH1)." (PMID 37026002, 2023).
Duchenne muscular dystrophy (6 papers, 2011 to 2024). Duchenne muscular dystrophy (DMD) is a neuromuscular disease characterized by rapidly progressive muscle weakness and wasting due to degeneration of skeletal, smooth and cardiac muscle. "As an example, the dystrophin-deficient mdx mouse model of Duchenne muscular dystrophy shows high Orai1 expression levels associated with increased SOCE activity." (PMID 38516893, 2024). "Immunodeficient patients harboring loss-of-function Orai1 mutations develop myopathies, while patients suffering from Duchenne muscular dystrophy display alterations in their Ca2+-handling proteins, including STIM proteins." (PMID 21798093, 2011). "Importantly, mouse models for dystrophic pathologies, like Duchenne muscular dystrophy, point towards an enhanced Ca2+ influx through Orai1 and/or TRPC channels, leading to Ca2+-dependent apoptosis and muscle degeneration." (PMID 21798093, 2011). "This seems in contrast with the up-regulation of STIM1 and Orai1 and the increased SOCE reported in mouse models for Duchenne muscular dystrophy." (PMID 21798093, 2011). "Consistent with the accumulated data from the mdx mouse model, human myoblasts isolated from Duchenne muscular dystrophy (DMD) patients showed a significant increase in SOCE but no increase in levels of TRPC1, Stim1 or Orai1." (PMID 30298191, 2019).
lung adenocarcinoma (6 papers, 2013 to 2022). A carcinoma that arises from the lung and is characterized by the presence of malignant glandular epithelial cells. "Although, this compound has affected both Orai1 and Orai3 expressions, these outcomes suggest that this drug could be a promising approach for cancer lung adenocarcinoma treatment." (PMID 27835593, 2016). "H23 is another lung adenocarcinoma cell line, in which Orai3 has been reported as a major component of SOC independently of Orai1." (PMID 34065942, 2021). "In lung adenocarcinoma, predominant studies have been performed on one lung cell line, A-549, where TRPC1 and Orai1 have been reported to contribute to SOCE." (PMID 24058448, 2013). "Immunostaining of tissues from patient cohorts with primary lung adenocarcinoma showed that platinum-based chemotherapy regimens increases the expression of Orai3, but not Orai1." (PMID 34065942, 2021). "Likewise, the in vitro, treatment with CDDP enhanced Orai3, but not Orai1 nor STIM1 or STIM2 expression in two lung adenocarcinoma cell lines: A549 and H23 cells." (PMID 34065942, 2021).
oral cancer (6 papers, 2020 to 2026). "Elevated expression of ORAI1 in human oral cancer led to sustained Ca2+ influx." (PMID 38672434, 2024). "Furthermore, previous studies have reported that silencing of Orai1 and Orai2 expression attenuate the Akt/mammalian target of rapamycin/NF-κB pathway in oral cancer cells, further supporting a role for Orai channels in NF-κB activation." (PMID 36623731, 2023). "siRNA-mediated knockdown of ORAI1 and STIM1 in Ca9-22 and OECM-1 oral cancer cell lines showed reduced proliferation, migration, and invasion of these cells." (PMID 35711942, 2022). "Lack of ORAI1 resulted in smaller oral cancer tumors and reduced MMP1 expression, which in turn diminished the activation of action potentials in trigeminal ganglia neurons." (PMID 38672434, 2024).
pancreatic ductal adenocarcinoma (6 papers, 2021 to 2024). An infiltrating adenocarcinoma that arises from the epithelial cells of the pancreas. "RP4010 has been also shown to reduce SOCE by inhibiting ORAI1 and the PI3K/Akt pathway when combined with chemo agents (gemcitabine and nab-paclitaxel) in pancreatic ductal adenocarcinoma cells." (PMID 36142596, 2022). "Our results in AML cells are, however, similar to our previous observations in pancreatic ductal adenocarcinoma (PDAC) cells, where ORAI1 also mediates SOCE and exhibits prosurvival and antiapoptotic roles in cell lines exposed to chemotherapy drugs." (PMID 35628366, 2022).
Thrombocytopenia (6 papers, 2020 to 2025). A reduction in the number of circulating thrombocytes. "SOCE deficiency in drosophila resulting from Stim or Orai downregulation impairs the flight capacities, and zebrafish embryos injected with mRNA containing STIM1 or ORAI1 GoF mutations display thrombocytopenia, highlighting the conservation of SOCE in specific tissues." (PMID 33250786, 2020). "The ORAI1-deficient patient presented with symptoms of HLH that were characterized by hepatosplenomegaly, anemia, thrombocytopenia, hyperferritinemia, and hypertriglyceridemia." (PMID 41200103, 2025). "On the other hand, anemia was only reported in 1 out of 6 TAM individuals resulting from the ORAI1 G98S mutation, while thrombocytopenia has not been reported in any Orai1G98S/+ patients." (PMID 39420094, 2024). "Although WT values are not reached, these data support a relevant effect of ORAI1 inhibition on the thrombocytopenia phenotype." (PMID 38516893, 2024). "Additional multi-systemic manifestations, including thrombocytopenia and hyposplenism, are observed in some individuals with TAM (typically in individuals with mutations in STIM1, but not ORAI1), which reflects in a clinical continuum with Stormorken and York Platelet Syndrome." (PMID 39420094, 2024). "However, the skin and spleen phenotypes were not relieved, and Stim1R304W/+Orai1+/− mice displayed the same thrombocytopenia and coagulation defects as their TAM/STRMK littermates." (PMID 35805973, 2022).
chronic kidney disease (5 papers, 2014 to 2023). Impairment of the renal function secondary to chronic kidney damage persisting for three or more months. "According to their results, Orai1-mediated Ca2+ entry is involved in the progression of renal fibrosis, which might lead to end-stage renal disease; however, the molecular mechanisms remain undetermined." (PMID 37259313, 2023). "Orai1+ cells are overexpressed in peripheral blood of patients suffering acute kidney injury, suggesting that Orai1 could possibly be a target in the acute kidney injury to chronic kidney disease transition." (PMID 37259313, 2023). "One finding of potential clinical significance about Orai1 positive cells is that they have been shown to be responsible for the chronic maladaptive action to AKI that eventually leads to interstitial fibrosis and chronic renal disease." (PMID 32521790, 2020). "In vivo, intra-renal expression of Orai1 persisted for days after AKI resolution and its inhibition prevented the transition to chronic kidney disease (CKD)." (PMID 32765535, 2020).
gastric cancer (5 papers, 2021 to 2024). A primary or metastatic malignant neoplasm involving the stomach. "Elevated Orai1 expression in gastric cancer is associated with advanced disease, more frequent recurrence and higher mortality rates." (PMID 36310590, 2022). "Clinically, ORAI1 overexpression is strongly linked to poor clinical outcomes in gastric cancer patients." (PMID 34055617, 2021). "Knockdown of ORAI1 resulted in reduced proliferation, migration, and invasion of two gastric cancer cell lines." (PMID 38672434, 2024). "For instance, ORAI1 has been shown to enhance gastric cancer cell migration and invasion by targeting MACC1 (metastasis-associated in colon cancer protein 1)." (PMID 38672434, 2024). "Additionally, it has been shown that the SOCE inhibitors, SKF-96365 and 2-APB, or the genetic knockdown of STIM1 and ORAI1 suppress the LPS-induced COX-2 production in gastric cancer cells." (PMID 37371732, 2023). "Interestingly, recent studies have shown that ORAI1 is overexpressed in many types of cancer, such as lung cancer, hepatocarcinoma, and gastric cancer." (PMID 34055617, 2021). "Elevated ORAI1 and STIM1 expression upregulated MACC1 expression and promoted tumor cell proliferation, metabolism, migration, and invasion in human gastric cancer." (PMID 35406521, 2022). "ORAI1 expression was found to be elevated in gastric cancer (GC) tissues compared to adjacent non-tumor tissues." (PMID 38672434, 2024).
Kawasaki disease (5 papers, 2016 to 2024). A rare inflammatory disease characterized by an acute febrile, systemic, self-limiting, medium-vessel vasculitis primarily affecting children. "The implication of ORAI1 in human cardiovascular abnormalities was highlighted by the reported association of ORAI1 mutations with Kawasaki disease (KD) susceptibility, which is the leading cause of cardiovascular complications during childhood." (PMID 33937254, 2021). "Finally, taking into consideration the causal associated between ITPKC polymophisms and Kawasaki disease, we have noted that overexpression of ITPKC in lung fibroblasts results in enhanced T cell activation (ORAI1, STIM1), which is associated with Kawasaki disease." (PMID 38991987, 2024).
multiple myeloma (5 papers, 2019 to 2023). "Overexpression of STIM1/Orai1 in multiple myeloma patients was closely associated with the shorter progression-free survival." (PMID 31252656, 2019). "In multiple myeloma patients, overexpression of STIM1/Orai1 was closely linked with shorter progression-free survival." (PMID 37259313, 2023). "Similarly, in multiple myeloma cells, inhibition of SOCE or silencing of STIM1 or Orai1 reduced cell viability and caused cell cycle arrest and apoptosis." (PMID 31252656, 2019). "Growing evidence has shown that numerous cancer types, including liver, lung, ovarian, breast, colon, and gastric cancer, as well as multiple myeloma, manifest increased SOCE and augmented expression of STIM1 or Orai1." (PMID 37259313, 2023). "For instance, STIM1 or Orai1 is overexpressed in tumor tissues when compared with noncancerous or precancerous tissues in patients with breast, cervical, colorectal, liver, lung, clear cell renal cancers, or multiple myeloma." (PMID 31252656, 2019).
neuroblastoma (5 papers, 2017 to 2025). Neuroblastoma (NB) is the most common solid, extracranial childhood tumor. "Of note, muscarinic acetylcholine receptors have been previously associated with STIM1/Orai1‐mediated SOCE in neuroblastoma cells; however, whether this is also the case in the heart remains to be determined." (PMID 35179826, 2022). "Moreover, expression of mutant HTT in mouse neuroblastoma and MSNs showed enhanced SOCE activation, which was reversed by RNAi knockdown of Orai1, TRPC1, or STIM1." (PMID 40169779, 2025).
non-small cell lung carcinoma (5 papers, 2016 to 2026). A group of at least three distinct histological types of lung cancer, including non-small cell squamous cell carcinoma, adenocarcinoma, and large cell carcinoma. "Recently, a new compound targeting calcium release-activated calcium (CRAC) channels including Orai1 and Orai3 channels has been developed by Rhizen pharmaceuticals for the treatment of the non-small cell lung cancer (Patent US 2011/0112058 A1,)." (PMID 27835593, 2016). "Interestingly, in non-small-cell lung cancer (NSCLC) cell line A549, down-regulated Orai1 expression promoted proliferation." (PMID 36612099, 2022).